IL6 (interleukin 6)
Diseases named in the same sentence as IL6 in open-access papers (continued):
Sharing a sentence is not in itself a finding about the gene and the disease.
heart failure (continued). "In rats with heart failure, IL-10 therapy significantly improved post-MI left ventricular function by reducing IL-6 and TNF-α, whilst in ischemia-reperfusion injury, IL-10 therapy reduced inflammation and cardiomyocyte death." (PMID 36140236, 2022). "Subsequent multivariate analysis identified that heart failure, IL-6, and hs-CRP were independently related to Log-LPS (P < 0.05)." (PMID 36285296, 2022). "IL-6 was also positively correlated with the severity of heart failure, the concentration of which was negatively correlated with left ventricular ejection fraction and overall survival." (PMID 34869661, 2021). "The purpose of this study was to investigate the utility of BNP, hsTroponin-I, interleukin-6, sST2, and galectin-3 in predicting the future development of new onset heart failure with preserved ejection fraction (HFpEF) in asymptomatic patients at-risk for HF." (PMID 33563287, 2021). "It has been reported that the serum level of IL-6 in the patients with heart failure is related to its severity." (PMID 33526170, 2021). "Analysis of transcript expression in the isolated hearts revealed that transcript expression of the proinflammatory cytokines Il6 and Il1b and the heart failure markers Anf and Bnp were significantly lower in Ccr2-KO mice." (PMID 34315245, 2021). "Since patients with heart failure exhibit elevated serum levels of IL-6 and sαKl12,14, we determined IL-6 and sαKl levels in these patients." (PMID 33479413, 2021). "It has been proved that the IL-6 level continues to increase progressively in patients with heart failure, with the aggravation of the NYHA functional class, and also, the high level is independently associated with the risk of mortality and hospitalization." (PMID 34683106, 2021). "Incidence rates of heart failure/1000 person-years, missing values and numbers of men in each C-reactive protein and IL-6 quartile." (PMID 33709785, 2021). "The established heart failure marker NTproBNP and IL-6 plasma levels were several-fold higher in both adult IPAH and CTD-PAH patients versus controls." (PMID 34445297, 2021). "The Kaplan–Meier survival curve of patients with heart failure according to IL-6 levels until the combined event (hospital admission, emergency care for HF, day hospital care for HF, and mortality) was not statistically significant (log-rank test = 0.097)." (PMID 33535417, 2021). "Regarding human studies, elevated IL-6 levels have been correlated with ventricular dysfunction, heart failure, arrhythmias and worse clinical outcomes, indicating a need for further study to clarify the role of IL-6 in CVD." (PMID 34603210, 2021). "The present study also revealed that inflammation-related cytokines (IL-6, TNF-α and adiponectin) were associated with heart failure severity." (PMID 34685378, 2021). "Markers reported to be elevated were D-dimer, NT-proBNP, C-reactive protein, serum ferritin, procalcitonin, and IL-6, which implies involvement in circulatory disorders, cardiac insufficiency, and inflammatory reactions." (PMID 33807280, 2021). "IL-6 expression is higher in patients with heart failure, and IL-6 levels correlate with disease severity and poor prognosis." (PMID 34696354, 2021). "Higher levels of inflammation-related cytokines (IL-6, TNF-α, adiponectin) are associated with heart failure severity and predict poor clinical outcomes." (PMID 34685378, 2021). "Although glucocorticoid and IL-6 were used, the patient suddenly developed heart failure heavily and died." (PMID 33708205, 2021). "A prolonged NF-κB activation promotes heart failure by evoking signals that induce chronic inflammation through the enhancement of cytokines including tumor necrosis factor, IL-1, and IL-6, commencing to endoplasmic reticulum stress responses and cell death." (PMID 32775437, 2020). "The level of inflammatory cytokines, IL-1 and IL-6 decreased in the resveratrol-treated heart failure patients compared to the placebo group." (PMID 33187089, 2020).
heart failure (continued). "And inflammation-related genes Mcp1, Tnfα, and Il6 and heart failure genes Anp, Bnp, and βMhc were up-regulated in the condition of Ang II infusion versus vehicle group." (PMID 33469534, 2020). "The levels of serum brain natrium peptide (BNP), growth stimulation expression gene 2 (ST2) and interleukin 6 (IL-6) all increased heavily in STAT3cKO mice, which were the key biomarkers of heart failure." (PMID 33365331, 2020). "The increasing level of IL-1 and IL-6 in the placebo group can be explained by the slow progression of heart failure in our enrolled population." (PMID 33187089, 2020). "Overexpression of Regnase-1 in cardiomyocytes decreased Il6 mRNA level in the heart and attenuated the development of myocardial inflammation and heart failure in a sTAC-operated wild-type mouse model." (PMID 31931613, 2020). "In patients with heart failure, high serum IL-6 concentrations have been detected, which correlates with left ventricular dysfunction severity." (PMID 32455143, 2020). "In particular, circulating levels of tumor necrosis factor-α (TNF-α), interleukin-6 (IL-6), IL-2, and IL-1β are known to correlate with disease severity in heart failure patients." (PMID 33321955, 2020). "Pro-inflammatory cytokines including tumor necrosis factor-α (TNF-α), interferon gamma (IFN-γ) and interleukin-6 (IL-6) appear to make a significant contribution to the pathophysiology of cardiomyopathy and heart failure." (PMID 31998452, 2019). "In comparison with the control group, the concentrations of interleukin-1α, interleukin-6, interleukin-8, and tumor necrosis factor were significantly higher in the serum of dogs with dilated cardiomyopathy complicated by Class II-IV heart failure." (PMID 31749587, 2019). "This indicates that, TIIA can reduce the IL-6 due to heart failure, thus alleviating ventricular remodeling." (PMID 31618407, 2019). "Of these, IL6, MMP2, and MMP9 are established risk correlates and mediators of adverse myocardial remodeling in heart failure." (PMID 30089854, 2019). "Finally, we provide the first link of IL-6 pathway to normal/impaired reperfusion, systolic function and diastolic function, adding to the increasing level of evidence linking interleukin pathways in MI and the future development of decreased cardiac function and the risk of heart failure." (PMID 30367209, 2019). "As revealed in previous clinical studies, the levels of IL-6 and IL-18 are increased in patients affected by heart failure." (PMID 31384408, 2019). "So far, it has been found that inflammatory cytokines associated with the heart failure mechanism include TNF-α, IL-6, IL-8, IL-10, IL-1α, IL-1β, IL-2, TGF-β, and IFN-γ." (PMID 31275453, 2019). "Pro-inflammatory cytokines, such as IL-1β, IL-6 and IL-13, play a significant role in regulating the progression from adaptive hypertrophy to heart failure." (PMID 31333486, 2019). "Previous studies of healthy individuals and people with heart failure recorded lower IL-6 concentrations in those reporting greater positive affect, but samples had only been analyzed under resting conditions." (PMID 29924291, 2019). "For instance, a large body of evidence indicates that circulating levels of IL-6 are increased in patients with heart failure and provide important prognostic information." (PMID 29695980, 2018). "IL6 stimulates angiotensinogen, serum amyloid P, fibrinogen, and orosomucoid-1 and inhibits transthyretin signifying men who developed heart failure had increased IL6 activity, whereas women with heart failure had decreased IL6 activity." (PMID 30132266, 2018). "Many excellent reviews cover the role of IL-6 signaling pathways in heart failure and cardiac remodeling." (PMID 29695980, 2018). "For instance, the levels of serum cytokines such as TNF-α, IL-6, and IL-1β are related to the severity of heart failure." (PMID 29511093, 2018). "IL-6 level is highly correlated with severity of heart failure, myocardial infarction and cardiac fibrosis." (PMID 29674727, 2018).
heart failure (continued). "Several studies have shown raised levels of inflammatory cytokines, such as tumor necrosis factor (TNF), interleukins from the IL-1 and IL-6 families in plasma, and circulating leukocytes in heart failure patients." (PMID 29900007, 2018). "Clinical trials also disclosed a strong correlation between elevated levels of circulating IL6 and heart failure severity and mortality in patients." (PMID 30662576, 2018). "Pro-inflammatory cytokines including TNF, IL-1β, and IL-6 are upregulated with decreased heart function, and are activated earlier in heart failure than the classic neurohormones." (PMID 29900007, 2018). "The levels of inflammatory cytokines (tumour necrosis factor-α [TNF-α], interleukin (IL)-1β, and IL-6) are increased in patients with heart failure." (PMID 29511093, 2018). "IS also upregulated mRNA expression of key cytokines playing role in heart failure progression: IL-1β, IL-6 and TNF-α, in cultured monocytic cells, indicating a pro-inflammatory effect of IS." (PMID 30200452, 2018). "Similar to mice, IL6 was a downstream regulator of sex differences during development of heart failure, as 28 of the 88 glycoproteins identified (32%) interact with IL6." (PMID 30132266, 2018). "It is well established that inflammatory cytokines including tumor necrosis factor-α, interleukin-1, and interleukin-6 (IL-6) play important roles in early and later stages of cardiac remodeling and heart failure." (PMID 29695980, 2018). "Serum concentrations of TNF-α, IL-1β and IL-6 were increased along with the severity of heart failure and the decrease of SNAQ scores as well." (PMID 29155861, 2017). "High levels of proinflammatory cytokines, including TNF-α, IL-6, IL-1β, and IL-2, have a profound effect on pathogenesis and prognosis in heart failure." (PMID 29201273, 2017). "In patients who developed heart failure higher initial levels of IL-6 were correlated with longer distance in 6MWT one month after surgery (R = 0.47, p < 0.001)." (PMID 29093735, 2017). "A recent meta-analysis and other studies found associations between IL-6 levels and CAD severity, coronary events, mortality and progression to heart failure." (PMID 28878828, 2017). "Elevated circulating levels of IL-6 have been described in patients with heart failure, and these higher levels are positively correlated with the presence and duration of cardiac arrhythmias and with the severity of disease and mortality risk." (PMID 28649227, 2017). "Recently, IL-6 transsignaling inhibition by sgp130 was put forward as a potential new treatment in heart failure." (PMID 27936014, 2016). "Frailty and heart failure would share a consistent correlation with some inflammatory biomarkers such as interleukin-6 and C-reactive protein." (PMID 27577747, 2016). "Taken together, serum NAMPT, by regulating the expression of different cytokines such as TNFα and IL-6, takes part in the heart failure progression in DCM patients." (PMID 26389889, 2015). "The study indicated serum NAMPT suppresses directly or indirectly the expression of important cytokines (IL-6 and TNFα) involved in heart failure progression in DCM patients." (PMID 26389889, 2015). "It was also shown that, CRP contributes to IL-6 expression which is a stronger prognostic predictor of heart failure than CRP." (PMID 25888309, 2015). "The level of circulating IL-6 is increased in heart failure patients correlating with severity of the disease." (PMID 25997003, 2015). "TNF-α and IL-6 circulating levels are elevated and correlate with disease severity in heart failure." (PMID 26539513, 2015). "Another study also showed that a higher circulating concentration of IL-6 indicated exacerbation of a hemodynamic condition and increasing heart failure symptoms in patients with congestive heart failure." (PMID 25551389, 2014).
heart failure (continued). "In both groups, a considerable improvement of ventricular function and clinical symptoms of cardiac insufficiency was achieved, as well as a decrease in the concentration of IL-6 and TNF-alpha." (PMID 23566246, 2013). "The inflammatory cytokines IL-6 and TNF-α, are known to promote LV dysfunction and play a pathogenic role in heart failure and DCM." (PMID 24086665, 2013). "TNF-α and IL-6 have both been repeatedly reported to correlate with cardiac contraction and relaxation deficits after burn trauma but also in heart failure patients." (PMID 23663695, 2013). "The expressions of IL-1β, TNF-α, and IL-6 were significantly higher in MI-induced heart failure treated with hGAPDH-SiRNA than in sham." (PMID 23874864, 2013). "Clinical trials demonstrated a correlation of increased levels of circulating IL-6 in patients and heart failure severity and mortality." (PMID 22574112, 2012). "In fact, elevated circulating levels of TNF-α and IL-6 have been reported as independent predictors of mortality in patients with heart failure." (PMID 22569420, 2012). "This is supported by the finding that levels of proinflammatory cytokines, including tumor necrosis factor (TNF)-α, interleukin (IL)-6 and IL-1β, increase during heart failure." (PMID 22569420, 2012). "IL6 plays a significant role in the induction of cardiomyocyte hypertrophy and inflammatory signaling and is a predictor of outcome in clinical heart failure." (PMID 22509276, 2012). "Arteriovenous IL-6 spillover in the peripheral circulation increases with the severity of heart failure, and an elevated level of plasma IL-6 was a predictor of mortality in patients with heart failure." (PMID 20682082, 2010). "Heart failure was associated with FGF23, IGFB-7, GDF-15, IL-6, and MyBPC3." (PMID 40496590, 2025). "Similarly, IL-6 inhibition with monoclonal antibodies like tocilizumab has shown potential in reducing AF incidence and improving outcomes in heart failure patients." (PMID 40901119, 2025). "However, if IL-6 is produced for too long or in excess, it can lead to heart enlargement and heart failure." (PMID 40535153, 2025). "In experimental models of cardiac injury and heart failure, IL-6 is consistently elevated." (PMID 40360833, 2025). "Additionally, GDF-15, insulin-like growth factor-binding protein-7 (IGFBP-7), NT-proBNP, and hsTropT predict heart failure hospitalization, while GDF-15 and IL-6 are associated with major bleeding events." (PMID 40744929, 2025). "Persistent and new lymphopenia were associated with older age, male sex; prior immunosuppression, heart failure, aspirin use, and normal body mass index; biomarkers of organ damage (renal and lung), and ineffective immune response (elevated IL-6 and viral nucleocapsid antigen levels)." (PMID 39810077, 2025). "All included studies: enrolled adult patients with acute or chronic heart failure, measured at least one inflammatory biomarker (IL-6, hs-CRP, or NLR), and reported multivariable-adjusted hazard ratios (HRs) for all-cause mortality and/or heart failure rehospitalization." (PMID 41375916, 2025). "In the heart, IL-6 has dual roles in both cardioprotection and cardiac failure." (PMID 40643523, 2025). "Experimental evidence showing the role of IL-6 signaling in the development of heart failure suggests that tocilizumab treatment could also be beneficial for patients with heart failure." (PMID 40360833, 2025). "Patients with heart failure often have an inflammatory response, and inflammatory markers such as high-sensitivity C-reactive protein (hs-CRP), interleukin-1β (IL-1β), and interleukin-6 (IL-6) play important roles in the occurrence and development of heart failure." (PMID 41333015, 2025). "Nonetheless, ongoing phase 3 trials, such as HERMES and ATHENA, are ongoing to evaluate IL-6 inhibition with ziltivekimab and may clarify whether more targeted approaches can provide clinical benefit in the heart failure scenario." (PMID 40828623, 2025).
heart failure (continued). "Fluid overload and consecutive high venous pressure in heart failure may increase pressure in the mesothelium, which could induce the release of several inflammatory markers (IL-6, IL-10, tumor necrosis factors)." (PMID 38667440, 2024). "Higher levels of IL-6 in younger patients with AF in our study may therefore in part reflect a higher degree of inflammation in the context of more advanced heart failure." (PMID 39202519, 2024). "IL-6 was also reported to play a role in post-MI heart failure and affect adverse remodeling." (PMID 38256155, 2024). "Many of the involved inflammatory markers, such as IL-6, CRP, TNF-α, IL-1β, and macrophage inhibitory factor (MIF), have been associated with post-MI hypertrophy, remodeling, persistent systolic dysfunction, heart failure, and mortality." (PMID 38558749, 2024). "IL-6 and related cytokines play crucial roles in the pathophysiology of heart failure." (PMID 39768841, 2024). "The role of IL-6 in the development of cardiac insufficiency remains unclear, despite an abundance of experimental and clinical research." (PMID 38338960, 2024). "Huo demonstrated that inhibiting the IL-6/STAT3 pathway could exert cardioprotective effects by mitigating oxidative stress-induced mitochondrial dysfunction in a heart failure model." (PMID 38319722, 2024). "Il-6 plays a central role in heart failure (HF) pathophysiology." (PMID 37446174, 2023). "Furthermore, it is consistent with clinical studies showing reduced IL-6 levels and soluble adhesion molecules in the serum of heart failure patients upon levosimendan treatment." (PMID 36979897, 2023). "During an episode of acute myocardial infarction (AMI), inflammatory processes involving fibrinogen, neutrophils, CRP, and IL-6 play a significant role in ischemia-reperfusion injury following reperfusion, leading to left ventricular remodeling and potentially developing heart failure." (PMID 37859889, 2023). "Gene–disease association information were as follows: HIF1A is associated with heart failure and cardiac hypertrophy; IL6 is associated with heart failure and cardiomyopathy; PTGS2 is associated with aortic aneurysms, heart failure, cardiac arrhythmias, cardiomyopathy, and CVD." (PMID 37283588, 2023). "Whether the reduction of Interleukin-6 levels is a mechanism for clinical improvement in patients or a marker of heart failure severity should be the subject of further research." (PMID 37445494, 2023). "It is noteworthy that circulating levels of interleukin (IL)-6-related cytokines are predictors of mortality in human heart failure, while the expression and post-translational modifications of STAT3 are severely reduced in myocardial cells in patients with dilated cardiomyopathy." (PMID 37019881, 2023). "On the other hand, the long-term IL6 signaling or an over-production of IL6R protein could potentially lead to cardiovascular diseases followed by heart failure." (PMID 35514439, 2022). "Interestingly, serum levels of interleukin-6 (IL-6) and TF are highly correlated in patients with heart failure, suggesting a crosstalk between inflammation and coagulation during LV remodeling." (PMID 36213278, 2022). "TNF and IL-6 biomarkers have been connected to the severity of heart failure, suggesting that they could be employed as biomarkers in the future." (PMID 35813433, 2022). "However, its role in heart failure is mainly to regulate cardiac remodeling and myocardial contractility by regulating IL-6 secretion, SERCA2 gene expression, and diastolic function of cardiomyocytes." (PMID 35242825, 2022). "Reactive oxygen species activate nuclear factor-kappa B, which leads to increased production of C-reactive protein, tumor necrosis factor-α, and interleukin-6, along with adhesion molecules such as E selectin, CD15, and CD32 that can cause endothelial damage, CHD, heart failure." (PMID 35287580, 2022). "TNF-α and IL-6 have been suggested as potential markers of heart failure in a number of studies." (PMID 35813433, 2022).